TRAF7 (TNF receptor associated factor 7)
Diseases named in the same sentence as TRAF7 in open-access papers (continued):
Sharing a sentence is not in itself a finding about the gene and the disease.
endothelial dysfunction (1 paper, 2025). In vascular diseases, endothelial dysfunction is a systemic pathological state of the endothelium (the inner lining of blood vessels) and can be broadly defined as an imbalance between vasodilating and vasoconstricting substances produced by (or acting on) the endothelium. "The evidence reviewed indicates that TRAF7 not only influences cellular responses to mechanical forces and inflammatory stimuli but also plays a significant role in preventing endothelial dysfunction and, consequently, cerebrovascular aging." (PMID 40868928, 2025). "Building on these findings, data suggest that targeting TRAF7 could offer novel therapeutic strategies to mitigate endothelial dysfunction and cerebrovascular aging." (PMID 40868928, 2025).
Fibrous Meningioma (1 paper, 2025). A WHO grade I meningioma characterized by the presence of spindle cells that form bundles in a collagen matrix. "It is well established that fibrous meningiomas commonly harbor NF2 mutations or chromosomal loss, whereas meningothelial tumors frequently carry TRAF7 and AKT1 mutations." (PMID 41154381, 2025).
hemangioblastoma (1 paper, 2020). "One patient from this group (F14) without either TRAF7, KLF4, or AKT1 mutations harbored a germline VHL mutation with VHL copy number loss in the tumor, and developed posterior fossa chordoid meningioma followed by hemangioblastoma 12 years later." (PMID 31963394, 2020).
hemorrhage (1 paper, 2025). Loss of blood from the vascular compartment to the exterior or into nonvascular body space as a result of rupture or severance of the blood vessels. "For example, research using genetic models has demonstrated that loss or dysregulation of TRAF7 in endothelial cells results in vascular abnormalities, including cerebral hemorrhages and impaired vessel integrity, highlighting its important role in maintaining vascular homeostasis." (PMID 40868928, 2025).
hyperostosis (1 paper, 2021). Excessive thickening of bone. "While bone invasion was associated with NF2 mutations, hyperostosis was seen more often together with TRAF7 aberrations." (PMID 34800210, 2021).
intracranial meningioma (1 paper, 2022). A meningioma that arises within the cranial cavity. "In contrast to AKT1-mutant intracranial meningiomas, where TRAF7 mutations are found to co-occur very frequently, we observed only a single AKT1-mutant SM case with a TRAF7 co-mutation." (PMID 35943573, 2022).
Kidney Cyst (1 paper, 2025). Abnormal fluid filled sac within the kidney, either acquired or congenital. "Previous research indicates that TRAF7 is linked to many developmental anomalies, including cardiac looping defects and other cardiac, craniofacial, and ciliary abnormalities, which in the setting of the kidneys manifested as kidney cysts and polycystic kidney disease." (PMID 40650197, 2025).
liver cancer (1 paper, 2023). An epithelial or non-epithelial malignant neoplasm that arises from the liver. "Cyld negatively regulates NF-kB, known to be one of the most important players in inflammation and liver cancer, and the MAPK signaling cascade by removing ubiquitin chains from signaling molecules, such as NEMO, TRAF2, TRAF6, TRAF7, TAK1 and RIP1." (PMID 37298191, 2023).
mesenchymal tumors (1 paper, 2026). "TRAF7 mutations are a rare occurrence in human cancer and have recently been described in a group of mesenchymal tumors with varying clinical course." (PMID 41811066, 2026).
peritoneal mesothelioma (1 paper, 2020). A benign or malignant mesothelial neoplasm that arises from the peritoneum. "TRAF copy number loss was observed in one WDPM case, whereas, several peritoneal mesothelioma cases harbored TRAF7 copy number alteration." (PMID 32545767, 2020).
skull base meningioma (1 paper, 2025). A meningioma that arises from the skull base. "TRAF7 mutations are found to be enriched in anterior skull base meningiomas, which are mesodermal in origin and tend to have non-NF2 genomic patterns." (PMID 40867323, 2025).
skull base tumors (1 paper, 2025). "Genotype (p = 0.004) and WHO grade (p = 0.002) were significantly associated with tumor location: NF2 alterations predominated in convexity and spine, while TRAKLS mutations (TRAF7, AKT1, KLF4, SMO) were enriched in lower-grade skull base tumors." (PMID 40951339, 2025).
Spindle Cell Tumor (1 paper, 2026). "Herein, we expand the spectrum of TRAF7-mutated fibromyxoid spindle cell tumors by reporting the first case to arise in bone." (PMID 41811066, 2026).
tubular adenoma (1 paper, 2016). A usually polypoid neoplasm arising from the glandular epithelium. "TRAF7 (NM_032271) displayed differential methylation for 17 CpG sites in tumor samples, while none of these were methylated in normal, tubular adenoma, and tubulovillous adenoma samples." (PMID 27688749, 2016).
tumor (47 papers, 2016 to 2026). "For tumours with mutations KLF4K409Q/TRAF7, Endoglin, E-cadherin and Anion exchange protein 2 were selected for further validation by Western blot." (PMID 40562609, 2025). "In tumours with AKT1E17K/TRAF7 mutations, specific antibodies were available for four up-regulated proteins (CLIC3, CRABP2, GMDS, and Pyruvate carboxylase)." (PMID 40562609, 2025). "Researches on TRAF7 and its associated tumor signal transduction have recently received significant attention." (PMID 40181456, 2025). "De novo point mutations in the TRAF7 gene occur in the germline, typically causing developmental disorders, and it can also be somatic, where they are strongly linked to tumor development." (PMID 41372821, 2025). "Using additional matched tumor pair analysis, mutations in TRAF7, ARID1A, and ERBB3 were identified as subclonal driver events at the time of recurrence." (PMID 38073632, 2023). "Because the majority of non-NF-2 meningioma driver mutations such as SMO, AKT1, SMARCB1, and TRAF7 normally occur mutually exclusive of NF-2, the expected rate of these mutations would be lower in high-grade tumor cohorts." (PMID 34638590, 2021). "The results indicated that TRAF7 was markedly associated with tumor size, histologic grade, and TNM stage." (PMID 34775479, 2021). "We discovered that TRAF7 was overexpressed in tumor tissues and the increased TRAF7 expression was closely associated with tumor size, histologic grade, TNM stage and poor prognostication." (PMID 34775479, 2021). "It is proposed that one of the paralogs of WDR86 is TRAF7, which has been implicated as a tumor suppressor by inducing apoptosis." (PMID 32539762, 2020). "Conversely, TRAF7 mutations showed an opposite trend without reaching statistical significance, with one patient having a TRAF7-mutated tumor undergoing surgery for recurrence (F21)." (PMID 31963394, 2020). "A pathogenic TRAF7 p.His521Arg variant was identified in 2/9 evaluable tumours (22.2%)." (PMID 41657107, 2026). "TRAF7 has a role in the regulation of innate and adaptive immune responses, but it is indeterminate whether the post-transplant tumor environment or immunosuppression may enrich for this mutation." (PMID 40510153, 2025). "In fact, TRAF7 mutations are emerging as prognostic molecular biomarkers in certain tumor types." (PMID 41372821, 2025). "We review how TRAF7 may function as an oncogene or a tumor suppressor, depending on the condition and underlying pathophysiology." (PMID 41372821, 2025). "Further analysis revealed upregulation of the oxidative phosphorylation pathway in AKT1E17K/TRAF7 tumours compared to other genetic backgrounds and normal meningeal tissue." (PMID 40562609, 2025). "KLF4K409Q/TRAF7 tumours exhibited reduced activity score for several signalling pathways, while NF2−/− tumours showed increase activity in pathways like Sirtuin signalling and Protein kinase A, albeit with generally lower protein level modulation." (PMID 40562609, 2025). "Proteomic analysis and validation of the NF2−/− tumours revealed that Annexin-3 (ANXA3) is over-expressed in all tumours analysed compared to AKT1E17K/TRAF7, KLF4K409Q/TRAF7 tumours, and normal meningeal tissue." (PMID 40562609, 2025). "The E3 ligase activity of TRAF7 can be involved in tumor suppressions by increasing apoptosis and reducing growth." (PMID 41372821, 2025). "Multiple comparisons among tumours show that the tumour AKT1E17K/TRAF7 shares more upregulated proteins (162 proteins) and only 3 down-regulated proteins compared to other groups." (PMID 40562609, 2025). "Ingenuity Pathway Analysis (IPA) showed significant activation of the oxidative phosphorylation pathway in AKT1E17K/TRAF7 tumours." (PMID 40562609, 2025). "Tumour tissue samples carrying AKT1E17K/TRAF7, KLF4K409Q/TRAF7, or NF2−/− mutations were processed for mass spectrometry analysis and compared to normal meningeal tissue (NMT)." (PMID 40562609, 2025).
tumor (continued). "TRAF7 overexpression can also promote tumor progression by impacting its downstream signaling pathways." (PMID 41372821, 2025). "For instance, TRAF7 (cg02678414) acts as a tumor suppressor, and its restoration inhibits AML proliferation via the KLF2-PFKFB3 glycolytic pathway." (PMID 40730747, 2025). "We found that TRAF7 inhibition induced cellular senescence, promoted G0/G1 arrest, and suppressed tumor proliferation." (PMID 40181456, 2025). "TRAF7 serves as a crucial intracellular adaptor and E3 ubiquitin ligase involved in signal transduction pathways, contributing to immune responses, tumor progression, and embryonic development." (PMID 38178633, 2024). "Accumulating evidence suggests that TRAF7 regulates tumor progression, inflammatory response, and apoptosis." (PMID 37845209, 2023). "Subsequently, cancer malignant behavior assays were performed and the results demonstrated that TRAF7 exerted predominant oncogene effects on tumor cells proliferation, migration, invasion in vitro." (PMID 34775479, 2021). "These ED groups correlated with tumor location and genetic profiling, with NF2 and chromatin remodeling gene mutations clustering in ED group #2, and TRAF7 mutations segregating in ED group #3." (PMID 31963394, 2020). "Next, many of the studies available focus on TRAF7’s roles in vascular development, inflammation, or tumor biology, with only limited work directly examining its function in neurovascular integrity, BBB regulation, or vascular cognitive impairment—all key hallmarks of cerebrovascular aging." (PMID 40868928, 2025). "Interestingly, this leads to TRAF7 having an oncogene role in some conditions and a tumor suppressor role in others." (PMID 41372821, 2025). "Although there is overlap between somatic mutations across different tumor types, there is no overlap with germline TRAF7 syndromic mutations." (PMID 41372821, 2025). "Neomorphic function of mutant TRAF7 homo- or heterotrimers is also a possibility, but it seems unlikely that identified missense TRAF7 mutations, which occur at different amino acid positions throughout CC and WD40 domains, would generate the same tumor growth signal." (PMID 36937440, 2023). "What’s more, the Western Blot assay proved the increased TRAF7 protein level in tumor tissues." (PMID 34775479, 2021). "It is evident from the previous studies that TRAF7 served as a tumor regulator in various cancers." (PMID 34775479, 2021). "However, by Sanger sequencing, we did not detect mutations at the established hotspots in AKT1, SMO, KLF4 and TRAF7, suggesting different tumor drivers acting in this age group." (PMID 34495383, 2021). "This study effectively determined that BAP1, CDKN2A and NF2 alterations occur in pleural effusion-derived tumour cells at a higher frequency than what is typically seen in MM tumour samples, as well as identifying high frequency alterations for the TRAF7 and LATS2 genes." (PMID 34900693, 2021). "In summary, WT TRAF7 appears to be a tumor suppressor that promotes cell apoptosis." (PMID 30294322, 2018). "In our sample set, we did not observe any atypical tumours that harboured mutations in TRAF7/KLF4, POLR2A or the Hedgehog pathway." (PMID 28195122, 2017). "In summary, we validated five highly expressed proteins as specific targets for different tumour mutational backgrounds: CLIC3, CRABP2, and GMDS for AKT1E17K/TRAF7 tumours, CD44 for KLF4K409Q/TRAF7 tumours and ANXA3 for NF2−/− tumours." (PMID 40562609, 2025). "TRAF1- TRAF7 were shown to be differentially expressed in various human cancers, and upregulation of TRAF expression was observed in tumor tissues compared to normal tissues in multiple cancer cohorts." (PMID 37389738, 2023). "TRAF7 mRNA level was tested in 49 cases of patients with HCC between tumor and adjacent non-tumor tissues by qRT-PCR." (PMID 34775479, 2021).
tumor (continued). "The group with sh-TRAF7 or CCNU treatment displayed a substantial reduction of the tumor growth as opposed to the control group." (PMID 40181456, 2025). "The KLF4K409Q/TRAF7 and NF2−/− tumours exhibited more down-regulation of proteins." (PMID 40562609, 2025). "Conversely, TRAF2, TRAF4, and TRAF7 displayed positive correlations with stromal, immune, and estimated scores, and negative correlations with tumor purity." (PMID 38825674, 2024). "Recently, TRAF7, a newly discovered member of the TRAF family, has been found to be involved in the development of several human malignancies, bringing it into the spotlight as a potential tumor suppressor gene." (PMID 37389738, 2023). "Furthermore, we observed a similar trend of mRNA expression of TRAF7 and MT1G in PDAC clinical samples, in which both of MT1G and TRAF7 were down-regulated in tumor tissues compared with the adjacent counterparts." (PMID 33537082, 2021). "Here, we detected the increased expression of TRAF7 in tumor compared with non-tumor tissues, and found the relation between TRAF7 expression with clinical characteristics and prognostication." (PMID 34775479, 2021). "The results indicated that the mRNA levels of TRAF7 in tumor tissues were upregulated compared with adjacent non-tumor tissues." (PMID 34775479, 2021). "Furthermore, the combination of TRAF7 inhibition with the second-line drug lomustine, as suggested by the National Comprehensive Cancer Network (NCCN) treatment guidelines, exhibited notable anti-tumor effects both in vitro and in patient-derived GSC assays." (PMID 40181456, 2025). "Moreover, continuous exposure to sublethal concentrations of TRAIL induces an NFkB-dependent increase in miR-21, miR-30c and miR-100, which downregulates expression of caspase 8, caspase 3, TRAF7 and Foxo3a, resulting in acquired resistance to TRAIL and the development of more aggressive tumours." (PMID 27140313, 2016). "Finally, TRAF7’s involvement in multiple signaling pathways (e.g., MEKK3-ERK5, NF-κB, Robo4) poses a challenge for therapeutic targeting, as perturbation of TRAF7 could lead to unintended effects in other cellular contexts, such as immune modulation or tumor suppression." (PMID 40868928, 2025).
cancer (18 papers, 2010 to 2026). A tumor composed of atypical neoplastic, often pleomorphic cells that invade other tissues. "Other variants in genes previously unreported in cancer have also described, such as TNF receptor-associated factor 7 (TRAF7), Krupple-like factor 4 (KLF4), and RNA-polymerase II (POLR2A)." (PMID 38730704, 2024). "Over half (53%, 174/326) of the TRAF7 coding-altering mutations are recurrently detected in at least two cancer patients." (PMID 30294322, 2018). "There are 376 different mutations of TRAF7 detected in human cancers, including 87% (326/376) coding-altering mutations and 13% (50/376) coding silent mutations." (PMID 30294322, 2018). "These highly interesting findings warrant further investigation of the in vivo functions of TRAF7 mutations in cancer pathogenesis using animal models." (PMID 30294322, 2018). "Of particular interest, missense mutations of six specific amino acids located within the C-terminal WD40 repeats, N520, H521, G536, S561, K615, and R641, are identified as mutation hotspots of TRAF7 detected in more than 15 cancer patients." (PMID 30294322, 2018). "Both T601 and R665 are located in the C-terminal WD40 repeats of TRAF7, which contain most mutation hotspots of TRAF7 detected in human cancers and are known to mediate the interaction of TRAF7 with MEKK3 or c-Myb." (PMID 30294322, 2018). "Although the functional significance of most TRAF7 mutations is currently unclear, the exceptionally high recurrence and clustering of missense mutations implicate TRAF7 malfunction as a critical pathogenic event in relevant human cancers." (PMID 30294322, 2018). "Furthermore, TRAF7 emerged as a high-risk gene across multiple cancer types, specifically in ACC, KIRC, LGG, LUAD, PAAD, and SKCM (HR > 1, P < 0.05)." (PMID 38825674, 2024). "Specifically, TRAF2, TRAF4, and TRAF7 are generally overexpressed in a pan-cancer context, and high expression levels of these genes are associated with poorer patient prognosis." (PMID 38825674, 2024). "This analysis revealed that TRAF1, TRAF2, TRAF3, TRAF4, TRAF6, and TRAF7 exhibit higher expression levels in cancer tissues, whereas TRAF5 is expressed at lower levels in these tissues." (PMID 38825674, 2024). "The emerging role of TRAF7 in the occurrence and progression of human cancers has been well-documented." (PMID 37845209, 2023). "As the last member of the TRAF family to be discovered, the function of TRAF7 in the occurrence and development of several human cancers has been well studied." (PMID 34775479, 2021). "TRAF7 is the last one of TRAFs family proteins to be found, which was demonstrated to be involved in a serious of cancers development." (PMID 34775479, 2021). "Further studies are required to clarify the roles and mechanisms of TRAF7 alterations in cancer pathogenesis." (PMID 30294322, 2018). "This was indeed the case, as the list of genes exclusively detected in cancer, including TRAF7, PRPS1, CDT1, and ZWINT, were previously reported as cancer marker genes." (PMID 20454660, 2010). "Our work suggests a mechanism by which Tri1 may alter TRAF7 signaling and has implications not only in the pathogenesis of C. trachomatis infections but also in understanding the role of TRAF7 in cancer." (PMID 38814079, 2024). "Our identification of Tri1 as a TRAF7 interactor provides an excellent opportunity to tease apart the mechanistic functions of this important host protein in numerous signaling pathways related to developmental biology, immunology, and cancer biology." (PMID 38814079, 2024). "In the current study, even though TRAF7 displayed high mRNA levels and protein levels in the TCGA cancer cohorts and human cancer cell lines, TRAF7 had little effect on the sensitivity of cancer cell lines to retinoic acid, probably due to the lack of a TRAF-C domain." (PMID 37389738, 2023). "TRAF2 and TRAF7 showed high protein levels in all cancer cell lines, except for the MeWo cells." (PMID 37389738, 2023).